TNF (tumor necrosis factor)
Diseases named in the same sentence as TNF in open-access papers (continued):
Sharing a sentence is not in itself a finding about the gene and the disease.
Hepatic steatosis (continued). "The intentions of the third experiment were to trigger the development of fatty liver in nonlactating cows through feed restriction, while using TRLP to determine whether blocking TNFα signaling would prevent this pathology." (PMID 29344353, 2018). "Moreover, the absence of TLR-3 protected against the development of hepatic steatosis after 33 weeks of HFD and reduced expression levels of TNFα in liver." (PMID 25867514, 2015). "VSL#3 intervention failed to modulate the liver steatosis score in ApoE−/− mice, but completely reverted the progression of liver inflammation and fibrosis in ApoE−/− mice exposed to DSS (p<0.05; n = 8–12), and reduced the liver content of TNFα, RANTES, ICAM-1, and MIP-1α (p<0.05; n = 5)." (PMID 23029000, 2012). "However, clinical evidences show that treatment with a TNF-α-specific blocking antibody-CDP571 could not alleviate the symptoms of metabolic diseases, which may be related to the multiple sources of TNF-α from KCs, DCs, neutrophils, and broad effects in fatty liver disease." (PMID 34956171, 2021).
myocardial infarction (432 papers, 2004 to 2026). Gross necrosis of the myocardium, as a result of interruption of the blood supply to the area, as in coronary thrombosis. "Meanwhile, CPC has a positive effect against acute myocardial infarction, causing down-expression of phospho-(Ser 536)-NFκB p65 and mRNA synthesis for IL-1β, IL-6, TNF-α, and INFγ." (PMID 39000141, 2024). "The release of multiple inflammatory mediators including IL-1 and TNF-alpha from burn wounds places burn victims at risk for myocardial infarction by similar mechanisms to those activated in patients with unstable angina." (PMID 39599987, 2024). "Pdpn, another downstream mediator of TNF-α, encodes a transmembrane glycoprotein that has been linked to cell motility, with Pdpn-expressing cells thought to play an important role in post-myocardial infarction cardiac fibrosis." (PMID 39056733, 2024). "In another retrospective study, subjects affected by CD (but not UC) exposed to a prolonged assumption of corticosteroids were associated with increased rates of myocardial infarction compared to anti tumor necrosis factor (TNF)-alfa use." (PMID 37260950, 2023). "The data revealed that, at week 5 post myocardial infarction, MA treatment was associated with significant reductions in circulating levels of both IL-6 and TNF-α compared to levels after treatment with vehicle." (PMID 36263604, 2023). "TNF-α is one of the most potent pro-inflammatory cytokines, rapidly upregulated and increased the risk of recurrent coronary events in myocardial infarction." (PMID 36713834, 2023). "Parallel to our findings, high sera levels of IL-10 and TNF-alpha were associated with admitted patients with myocarditis and those with acute myocardial infarction." (PMID 36967438, 2023). "It was also shown that in experimental myocardial infarction in 5-lipoxygenase-deficient mice there was an increase in neutrophil infiltration and tumor necrosis factor (TNF) expression." (PMID 36011386, 2022). "IL-27′s enhancement of TNF-α mediated upregulation of adhesion molecules and pro-inflammatory IL-6 in blood monocytes of patients with acute myocardial infarction (MI) makes it high CVD risk associated." (PMID 35327515, 2022). "Increased TNF-α expression is associated with the development of several cardiac diseases, such as myocardial infarction, ventricular remodeling, and CCC." (PMID 34722343, 2021). "Wu and Poon found that psoriatic patients treated with TNF-α inhibitors were at lower risk of myocardial infarction than untreated patients." (PMID 34829740, 2021). "For example, it has been reported that patients treated with inflammation using TNF-α inhibitors have a 21% lower risk of myocardial infarction (MI) than patients treated with topical agents or phototherapy." (PMID 34551806, 2021). "Next, we set out to determine the underlying association between heart attack and triglycerides while controlling for TNFα, IL6 and HDL-C." (PMID 33510184, 2021). "Elevated levels of inflammatory biomarkers such as C-reactive protein (CRP), interleukin-6 (IL-6), or tumor necrosis factor (TNF) have been shown to be associated with an increased risk of myocardial infarction and mortality." (PMID 33481059, 2021). "TNF-α signaling is also implicated in cardiac remodeling, and inhibiting TNF-α in the acute phase of Myocardial Infarction (MI) promotes ventricular rupture by reducing fibrosis via the activation of matrix metalloproteinase-9." (PMID 34539391, 2021). "TNF-α has been linked to increased cardiovascular events in a 5-year period post myocardial infarction as well as CAD complexity." (PMID 34988343, 2021). "Myocardial infarction and reperfusion injury have been associated with the activation of pro-inflammatory cytokines such as TNF-α, IL-1β, and IL-6, and this activation promotes leukocyte activation and extravasation into the LV infarcted area." (PMID 33313409, 2020).
myocardial infarction (continued). "Tumor necrosis factor-alpha (TNF-α) is an important pro-inflammatory mediator and is linked with the risk of recurrent myocardial infarction and death." (PMID 33489600, 2020). "In humans, anti-inflammatory treatments targeting TNFα or IL-1β are associated with decreased risk of myocardial infarction and overall cardiovascular events." (PMID 31461490, 2019). "Few studies have shown the effect of down regulation of 5-LO however, one study reported an increased neutrophil infiltration and TNF expression within the myocardial infarction area of 5-LO deficient mice." (PMID 30555831, 2018). "A retrospective study enrolling RA patients initiating biologic therapies, patients treated with abatacept were characterized by a lower risk of myocardial infarction in comparison to patients on TNFα-i therapy." (PMID 30619884, 2018). "A recent prospective study with a longer follow-up (median 5 years) demonstrated that TNFα-i therapy in RA patients is associated with a significant reduction of 39% in the risk of myocardial infarction in comparison to DMARD therapy." (PMID 30619884, 2018). "Specifically, TNF inhibitors were linked to reduced incidence of myocardial infarction compared with topical/photo or methotrexate treatment (RR, 0.73; 95% CI, 0.59 to 0.90; and RR, 0.65; 95% CI, 0.48 to 0.89; respectively)." (PMID 29295598, 2017). "Use of TNF antagonists is associated with a reduced incidence of myocardial infarction as compared to topical treatment." (PMID 26633680, 2015). "The presence of depressive symptoms in patients who had suffered from myocardial infarction was associated with increased TNF-α levels." (PMID 25097498, 2014). "The circulating levels of C-reactive protein (CRP), tumor necrosis factor-α (TNF-α), and interleukin-6 (IL-6) are positively correlated with the risk of primary and recurrent myocardial infarction and death." (PMID 24192015, 2013). "There is a significant association between the TNF-α-308 polymorphism and the occurrence of ST-elevated myocardial infarction (STEMI), which suggests that this polymorphism plays a role in the pathogenesis of cardiac ischemic damage." (PMID 22408428, 2012). "Patients receiving TNF-α inhibitors had a 48% reduction in the risk of myocardial infarction (P = 0.0062)." (PMID 23209897, 2012). "In keeping with these observations, data from a recent systematic review confirmed that anti-TNF-alpha therapy was associated with a reduced risk for all CV events, myocardial infarction, and cerebrovascular accidents." (PMID 22899879, 2012). "Our findings are in line with human studies that found that risk of cardiovascular events, including myocardial infarction is associated with increased blood levels of inflammatory cytokines such as TNF-α and its receptors, adhesion molecules, and CRP." (PMID 22745783, 2012). "A lower risk for all CV events and myocardial infarction was also associated with a longer exposition-duration to TNF-α blockers (HR 0.42; 95% CI 0.21 to 0.81; P < 0.05)." (PMID 18325087, 2008). "Plasma TNF-α levels predicted second myocardial infarction, and have been associated with common carotid intima-media thickness." (PMID 15485576, 2004). "It induces cells to produce and release a multitude of inflammatory factors, such as IL-6, IL-1β, and TNF-α, which mediate the cascade of inflammatory responses, causing the necrosis of cardiomyocytes, an increase in myocardial infarction area, and a decrease in cardiac function." (PMID 40809170, 2025). "The hydroalcoholic extracts of aerial parts of A. italica exhibited significant anti‐inflammatory potentials shown by down‐regulation of TNF‐α, IL‐1β, and IL‐6 in myocardial infarction mice model, which were mainly linked with its total flavonoid and polyphenolic contents." (PMID 39723071, 2024).
myocardial infarction (continued). "Chronic kidney disease activates vascular inflammatory processes and as consequence high levels of inflammatory biomarkers such as interleukin-6 (IL-6), C-reactive protein (CRP), and tumor necrosis factor (TNF) are associated with an increased risk of myocardial infarction and mortality." (PMID 35453821, 2022). "A rise in TNF levels has been seen after a myocardial infarction, but it is unclear if these higher levels, found months after the initial event, are associated with an increased risk of subsequent heart attacks." (PMID 35813433, 2022). "In the clinical setting, it has long been shown that increased circulating TNF-α concentrations may signify an excess risk of recurrent cardiovascular events in patients after myocardial infarction." (PMID 36555579, 2022). "Moreover, the increased expression of ADAM17, as well as of TNF-α was associated with rupture of atherosclerotic coronary plaques in patients with myocardial infarction." (PMID 33117379, 2020). "Furthermore, according to the approach that investigates negative genes with high positive probability as output by the DNN, the gene AGT is associated with brain diseases and neoplasms; and the gene TNF is associated with myocardial infarction." (PMID 31845988, 2020). "However, kidney ischemia-reperfusion injury, myocardial infarction, and systemic inflammation associated with A20 deficiency or high-dose tumor necrosis factor (TNF) were ameliorated by RIPK3 deficiency." (PMID 28423682, 2017). "In a study on rats with myocardial infarction (MI), Qili Qiangxin induced heart muscle regeneration and improved cardiac function through regulating the balance between tumor necrosis factor (TNF)-α and interleukin (IL)-10, factors closely associated with inflammatory processes in HF." (PMID 27402016, 2016). "This is potentially of considerable importance since RA is known to increase the risk of thrombotic events such as myocardial infarction and this risk may be modified by TNF-α inhibitors." (PMID 19265537, 2009). "Furthermore, during myocardial infarct, it has been described a significant stimulation of D3 activity, probably caused by the chronic inflammation promoted by the Tumor Necrosis Factor- α (TNF-α) and the Interleukin-6 (IL-6) release, thus complicating the hypothyroid condition." (PMID 36676947, 2022). "In further studies, high IL-10/TNF-α ratios were associated with a better outcome in children with malaria infections, with a reduced infection susceptibility in severe burn injury patients or with improved outcome in experimentally induced myocardial infarction." (PMID 33582876, 2021). "Abatacept may be associated with lower risk of myocardial infarction in comparison with TNFα-i." (PMID 30619884, 2018). "A final–and atypical–finding comes from patients with acute myocardial infarction in an Iranian hospital; among 4 cytokines measured in both the circulation and saliva, high inter-compartmental associations (all with p values of <0.001) were found for three: IL-2; IL-6; and TNF-α." (PMID 26075910, 2015). "Cardiac overexpression of TNF-α has been associated with cardiac hypertrophy and fibrosis, as well with left ventricular dysfunction and IL-6 has been also described as an inducer of myocardial damage by promoting LV dysfunction and cardiac hypertrophy under acute myocardial infarction." (PMID 23497124, 2013). "Positive correlations have been established between acute myocardial infarction and elevated levels of pro-inflammatory cytokines such as TNF-α, IL-6, and IL-1β." (PMID 41599430, 2026). "Elevated levels of TNF-α, both in circulation and the myocardium, are observed in dilated cardiomyopathy, myocardial infarction, and LV pressure overload, and are thought to contribute to ventricular remodeling." (PMID 40257974, 2025).
myocardial infarction (continued). "In a mouse model of myocardial infarction, YAP/TAZ deficiency reduced pro-inflammatory cytokines such as TNF-α and IL-6 while increasing Arg1 expression, ultimately improving infarct healing and cardiac function." (PMID 41346626, 2025). "TNF-α affects the short-term and long-term prognoses for myocardial infarction by inhibiting the generation of CCC." (PMID 41278503, 2025). "Etanercept, a TNF‐α blocker, is also undergoing clinical trials in patients with acute myocardial infarction (NCT01372930)." (PMID 40126336, 2025). "TNF-α and IL-6 are key pro-inflammatory cytokines involved in the pathophysiological response following myocardial infarction." (PMID 40918185, 2025). "The different levels of TNF-α expressions after myocardial infarction are related to the various grades of CCC information." (PMID 41278503, 2025). "In a later study of myocardial infarction in rats, MR-409 reduced plasma levels of interleukin (IL)-2, IL-6, IL-10 and tumor necrosis factor-alpha (TNF-α), cytokines related to inflammation and fibrosis." (PMID 39883351, 2025). "Previous studies have shown that olive oil can improve ventricular remodeling after myocardial infarction by suppressing TNF-α and oxidative stress." (PMID 41567391, 2025). "M1 macrophages produce inflammatory cytokines such as TNF-α and IL-6, which drive the progression of atherosclerotic plaques and contribute to myocardial damage post-myocardial infarction (MI)." (PMID 39736852, 2025). "Monocytes in the acute phase of myocardial infarction differentiate into pro-inflammatory M1 macrophages, which secrete IL-6 and TNF-α, further activating local inflammatory pathways." (PMID 40918184, 2025). "Suppressing TNF-α production and activity in the early acute phase of myocardial infarction has been shown to improve cardiac function." (PMID 39368019, 2025). "Plasma TNFα in humans predicts incident myocardial infarction, though the mechanism for the proatherogenic role of TNFα is unclear." (PMID 40558641, 2025). "Lactobacillus can improve cardiac function by improving inflammation and myocardial damage after AMI, reducing the levels of tumor necrosis factor-α and lipid peroxidation in myocardial infarction rats." (PMID 39863867, 2025). "Elevated circulating TNF-α levels in ACS patients, including several months after myocardial infarction, are associated with an increased risk of recurrent coronary events, heart failure, and mortality." (PMID 41511355, 2025). "Analysis through immunohistochemistry on myocardial tissue revealed that the mVNS treatment was effective in reducing macrophage infiltration and lowering the levels of inflammatory factors (such as IL-1β and TNF-α) in the plasma post-myocardial infarction." (PMID 40001724, 2025). "The current findings of cytokines (TNF-α, TNFR2, and VEGF) associated with CVDs are congruent with the results of previous studies for TNFR2 in myocardial infarction in the Swedish population and TNF-α." (PMID 39409080, 2024). "In animal models of myocardial infarction, heightened levels of tumor necrosis factor (TNF) within the myocardium directly correlate with increased production of local MMP-9 and MMP-2." (PMID 39432214, 2024). "In acute myocardial infarction, the myocardium also releases IL-6 and TNFα, and plasma levels of these cytokines increase after a brief episode of coronary artery blockage." (PMID 38397797, 2024). "Our findings contribute to understanding the potential of TNF-α-treated BMSC-derived exosomes as a therapeutic approach for myocardial infarction." (PMID 38766777, 2024).